CCR1 (C-C motif chemokine receptor 1)
Description:
Chemokine receptor that plays a crucial role in regulating immune cell migration, inflammation, and immune responses. Contributes to the inflammatory response by recruiting immune cells, such as monocytes, macrophages, T-cells, and dendritic cells, to sites of inflammation for the clearance of pathogens and the resolution of tissue damage. When activated by its ligands including CCL3, CCL5-9, CCL13-16 and CCL23, triggers a signaling cascade within immune cells, leading to their migration towards the source of the chemokine. For example, mediates neutrophil migration after activation by CCL3 leading to the sequential release of TNF and leukotriene B4 (By similarity). Also mediates monocyte migration upon CXCL4 binding. Activation by CCL5 results in neuroinflammation through the ERK1/2 signaling pathway (By similarity).
Synonyms: CD191; CMKBR1; SCYAR1; CKR-1; MIP1aR; CKR1; HM145
Tractability: Small molecule: a drug acting on it is in phase 2 or 3 trials; a structure with a bound ligand is known; a high-quality ligand is known; it belongs to a druggable protein family. Antibody: UniProt places it where antibodies can reach, with high confidence; its Gene Ontology location is reachable by antibodies, with high confidence; UniProt predicts a signal peptide or a membrane-spanning region. PROTAC: ubiquitination databases record sites on it; its protein half-life has been measured; a small molecule that binds it is known.
Target class: Chemokine receptor; Peptide receptor (family A GPCR); Family A G protein-coupled receptor; CC chemokine receptor; Membrane receptor
Chemical probes: BAY-3153 (high quality), BI 639667 (high quality), CHEMBL2180528
Gene: Protein-coding gene on chromosome 3 (46,201,711 to 46,208,378, reverse strand). Ensembl gene ENSG00000163823.
Subcellular location: Cell membrane
Pathways (Reactome):
Signal Transduction: Chemokine receptors bind chemokines; G alpha (i) signalling events
Immune System: Interleukin-10 signaling
Gene Ontology:
Molecular function: C-C chemokine binding; C-C chemokine receptor activity; chemokine (C-C motif) ligand 5 binding; chemokine (C-C motif) ligand 7 binding; chemokine receptor activity; phosphatidylinositol-4,5-bisphosphate phospholipase C activity; protein binding; G protein-coupled receptor activity
Biological process: calcium ion transport; cell-cell signaling; chemokine-mediated signaling pathway; exocytosis; immune response; intracellular calcium ion homeostasis; monocyte chemotaxis; negative regulation of bone mineralization; negative regulation of gene expression; positive regulation of calcium ion transport; positive regulation of cell migration; positive regulation of cytosolic calcium ion concentration; positive regulation of ERK1 and ERK2 cascade; positive regulation of inflammatory response; positive regulation of monocyte chemotaxis; positive regulation of osteoclast differentiation; calcium-mediated signaling; cell adhesion; cell chemotaxis; cell surface receptor signaling pathway; chemotaxis; cytokine-mediated signaling pathway; dendritic cell chemotaxis; G protein-coupled receptor signaling pathway, coupled to cyclic nucleotide second messenger; inflammatory response; and 4 more
Cellular component: external side of plasma membrane; plasma membrane; cytoplasm; membrane
Genetic constraint (gnomAD): Loss-of-function variants: 1 observed, 0.44 expected, observed/expected ratio (o/e) 2.27. That is too few expected variants to judge how well the gene tolerates losing a copy. Missense variants: 349 observed, 456.15 expected, observed/expected ratio (o/e) 0.77, 90% interval 0.7 to 0.84. Synonymous variants: 207 observed, 193.11 expected, observed/expected ratio (o/e) 1.07, 90% interval 0.96 to 1.2.
Homologues: Orthologues: chimpanzee CCR1 (99% identical), macaque CCR1 (88% identical), pig CCR1 (83% identical), rabbit CCR1 (82% identical), mouse Ccr1 (80% identical), rat Ccr1 (80% identical), dog CCR1 (79% identical), rat Ccr1l1 (66% identical), mouse Ccr1l1 (63% identical), tropical clawed frog ccr2 (49% identical), zebrafish cabz01093075.1 (39% identical), zebrafish si:ch211-207g17.3 (39% identical), and 4 more. Paralogues in human: CCR3 (63% identical), CCR5 (55% identical), CCR2 (54% identical), CCR4 (47% identical), CCRL2 (39% identical), CCR8 (39% identical), CX3CR1 (39% identical), ACKR2 (36% identical), CCR7 (33% identical), CCR9 (33% identical), XCR1 (32% identical), CCR6 (32% identical), and 11 more.
Diseases named in the same sentence as CCR1 in open-access papers:
CCR1 is named in the same sentence as 237 diseases in open-access papers, as found by Europe PMC text mining. Sharing a sentence is not in itself a finding about the gene and the disease. The quoted sentences say what the papers report.
COVID-19 (42 papers, 2020 to 2025). A disease caused by infection with severe acute respiratory syndrome coronavirus 2. "Given that a consistent molecular symptom of severe COVID-19 response is elevated cytokine levels, particularly elevated CCR1, this variant is a prime causal variant for the association between this genetic haplotype and severe COVID-19." (PMID 36763080, 2023). "Several previous GWASs have reported genetic variants in CCR1 are associated with COVID-19 susceptibility at a genome-wide significant level." (PMID 35172892, 2022). "The second locus (index SNP: rs3136673, Pmeta = 5.90 × 10–10) was originally significant associated with COVID-19 (P = 6.87 × 10–9), the mapped gene CCR1 involved in heart and blood communication in cardiac diseases." (PMID 36187959, 2022). "The eQTL analysis encompassing 22 lead SNPs identified 29 novel genes in addition to 4 genes (i.e., SLC6A20, FYCO1, CXCR6, CCR1) previously reported by the severe COVID-19 GWAS group to be associated with rs11385942 at locus 3p21.31." (PMID 34027315, 2021). "Furthermore, alleles in Block A of the introgressed haplotype, which exhibit the strongest GWAS associations with COVID-19 severity, all act as down-regulating eQTLs for CCR1 in healthy whole blood samples." (PMID 36763080, 2023). "In light of the efforts of multiple groups devoted to narrowing down the genes mediating the COVID-19 severity association, we conclude that several genes at this locus on chromosome 3, including CCR1 and CCR5, display promising evidence for having a role in the underlying biological mechanisms." (PMID 36763080, 2023). "This DMR was in close proximity to the genetic risk locus linked to severe COVID-19, aligning with previous research indicating that upregulation of CCR1 in macrophages is related to severe COVID-19 outcomes." (PMID 40119174, 2025). "For example, in the severe COVID-19 phenotype, CCR1 and CCR5 are upregulated relative to their expression levels in moderate cases of the disease and we saw evidence of upreglation by introgressed alleles in our mock infection experiment as well." (PMID 36763080, 2023). "Of these genes, 7 are chemokine receptor genes (CCR1, CCR2, CCR3, CCR5, CCR9, CCRL2, and CXCR6), which are likely linked to the segment’s association with COVID-19 severity." (PMID 36763080, 2023). "By performing a MAGMA gene-level association analysis, we observed that 25 genes including CXCR6, CCR1, IFNAR2, IL10RB, and OAS1 were significantly associated with severe COVID-19 (FDR < 0.05)." (PMID 35172892, 2022). "Analysis of molecular networks commonly affected both by hypertension and by severe COVID-19 highlighted CCR1/CCR5 and IL10RB signaling, as well as Th1 and Th2 activation pathways, and also a potential for a shared regulation with multiple sclerosis." (PMID 36160003, 2022). "We also observed increased levels of CCL5 and CCL3, expressed in NK cells, that interact with the CD191 receptor (CCR1), and whose inhibition potentially suppresses immune hyperactivation in critical COVID-19 patients." (PMID 36443794, 2022). "In this regard, a gene cluster on chromosome 3 containing CCR1, CCR3, CXCR6, and CCR9, has been identified as a major risk factor for COVID-19 at the genome-wide level (Zeberg and Pääbo, 2020)." (PMID 36320810, 2022). "The genetic liabilities to elevated blood pressure and to severe COVID-19 intertwine, and among them, the immune-regulating receptors CCR1/CCR5 and IL10RB signaling pathway are highlighted in the common effective tissue of the lung." (PMID 36160003, 2022). "Our analysis revealed a strong signal of coherence between COVID-19 and M05B medications, with chemokine receptor genes CCR1, CCR3 and LZTFL1 as lead hits." (PMID 36156592, 2022). "Additionally three genes (CCR1, FYCO1, and XCR1) were not only associated with COVID-19, but also at least two cardiac traits." (PMID 36187959, 2022).
COVID-19 (continued). "Thus, inflammatory CCR1+ CD16+monocytes among severe COVID-19 patients potentially accelerate the activation of memory CD8+T cells." (PMID 35172892, 2022). "Notably, we prioritized 34 risk genes, including potential causal genes of CXCR6, CCR1, and ABO, to be associated with severe COVID-19." (PMID 35172892, 2022). "However, classical and intermediate monocytes from individuals recovered from severe COVID-19 had reduced expression of pro-inflammatory chemokine receptors CCR1 and CCR2 (Bonferroni-adjusted P-value range 0.03–2.07 × 10−9)." (PMID 36433939, 2022). "According to GeneAtlas, FYCO1 variant rs33910087 is a highly significant modifier of monocyte percentage (p = 3.85 × 10−46), and based on GTEx v8, this variant is also an eQTL for several protein-coding genes previously associated with COVID-19 (CXCR6, FYCO1, SLC6A20, CCR1, LZTFL1)." (PMID 35910207, 2022). "Additionally, these highly expressed genes among CCR1+ CD16+monocytes have a remarkably higher proportion of druggable genes and COVID-19-associated druggable genes (P ≤ 0.01)." (PMID 35172892, 2022). "Notably, four chemokine receptors identified by our study (CXCR6 in the ileum, CCR1/2 and CCR9 in both ileum and colon) are coded in a genomic region found to be a COVID-19 risk locus on chromosome 3, further validating our predictions." (PMID 35501398, 2022). "Interestingly, CCR1 is expressed on blood myeloid cells such as monocytes and neutrophils, and it is upregulated on COVID-19 patients." (PMID 34262570, 2021). "Furthermore, by integrating the surface target and drug-target binding databases with RNA-sequencing data of severe COVID-19, we identified candidate surface and druggable targets including CCR1 and FPR1 for drug delivery as well as molecular imaging." (PMID 34239034, 2021). "The CCR1 plays a pivotal role in the recruitment of effector immune cells to the site of inflammation, and the pharmacologic inhibition of this gene may suppress immune hyper-activation in severe COVID-19." (PMID 35172892, 2022). "Individuals that suffered from severe COVID-19 show reduced frequencies of T cell, mucosal-associated invariant T cell (MAIT) and dendritic cell (DC) subsets and altered chemokine receptor expression on several subsets, such as reduced levels of CCR1 and CCR2 on monocyte subsets." (PMID 36433939, 2022). "Both CCR1 and CCR2 interact with pro-inflammatory chemokines which are upregulated in the lungs of severe COVID-19 patients." (PMID 36433939, 2022). "To gain refined insights into CCR1+ CD16+monocytes and CXCR6+ memory CD8+T cells, we examined the cellular interactions among cell populations in PBMCs and BALFs according to the COVID-19 disease status using the CellChat algorithm." (PMID 35172892, 2022). "Seven of our significant genes higher (GALNT14, OAS1, CCRL2, OAS3, CCR1, OAS2, SIPA1L2) in COVID-19 and two lower (HLA-DPB1, HLA-DQA2) were identified to overlap." (PMID 34335605, 2021). "Moreover, CCR1 was reported to be expressed by CD16+ monocytes, while CCR5, CCR9, and CXCR6 by T cell subsets in COVID-19 patients." (PMID 39811276, 2025). "In addition, the expression of CCR1 and CCR2 was reduced in peripheral blood monocytes from COVID-19-recovered patients." (PMID 39811276, 2025). "The genes associated with EDS or COVID-19 severity are distributed on all chromosomes (except for Y and 8, 13, 16, 20 for COVID-19) with clusters at 2q32.2 (COL5A2/COL3), 3p24.1 (SCN5/10/11A), 11q23.3 (SCN2/4B), and 21q22.3 (COL6A1/A2) for EDS and at 3p22.2 (CCR1/5-CXCR6) for COVID-19 (column L)." (PMID 37504295, 2023). "Chemokine receptors, such as CCR9, CXCR6, CCR1, CCR3, CCR5, and CCR2, are all located on chromosome 3 and already showed significant associations with COVID-19 without network boosting." (PMID 36291657, 2022). "Furthermore, we observed reduced expression of CCR1 and CCR2 on monocyte subsets from individuals recovered from severe COVID-19." (PMID 36433939, 2022).
COVID-19 (continued). "Individuals that suffered from severe COVID-19 showed reduced frequencies of T cell, MAIT cell and dendritic cell (DCs) subsets and altered chemokine receptor expression on several subsets, such as reduced levels of CCR1 and CCR2 on monocyte subsets." (PMID 35291290, 2022). "Additionally, there are 1155 and 22 ligand candidates for CCR1 and GPR183, surface targets enriched in severe COVID-19, in BindingDB, respectively." (PMID 34239034, 2021). "CCR1 and FPR1 were highly expressed in macrophages enriched in the severe COVID-19 group." (PMID 34239034, 2021). "The MCODE plugin in Metascape was used to determine important modules and related hub genes in the constructed PPI network, and chemokines such as CCR1, CCL19, CXCL10, and CXCL16 were identified to present the most obvious changes in COVID-19 disease progression." (PMID 33195212, 2020). "And the subsequent PPI analysis results in our study also confirmed that chemokines related to inflammatory responses, such as CCR1, CCL19, and CXCL10, and the immune response-related gene FPR1 presented significant expression changes in the progression of COVID-19." (PMID 33195212, 2020). "Furthermore, COVID-derived PBMCs and monocytes had upregulated expression of migration markers, including endothelial adhesion molecules, including L-selectin and intercellular adhesion molecule 1 (ICAM1), and CC/CXC chemokine receptors (CCR1, CXCR1), as a function of the severity of COVID-19." (PMID 37310504, 2023). "Furthermore, upon bacterial challenge, a similar pattern of cell surface receptor phenotype with reduced expression of CXCR1, CXCR2, CXCR3, CCR1, CCR5 and the maturation marker CD15, with increased expression of CXCR4 and CD66b was found in neutrophils from acute-phase COVID-19 patients." (PMID 35007290, 2022). "Thus, altered expression of CCR1 and CCR2 at steady state might influence the severity of COVID-19." (PMID 36433939, 2022). "Similar to CCR1− CD16+monocytes, we observed no remarked difference of cellular interactions between normal controls and COVID-19 patients among CXCR6− memory CD8+T cells (P > 0.05)." (PMID 35172892, 2022). "Concentrations of select chemokines (CXCL8, CXCL10, CCL2, CCL3, CCR1) and complement factors (C2, C9, CFD, C4BPA, C5AR1, CR1) were examined at mRNA and protein levels with regard to a COVID-19 course (ICU vs. non-ICU group) and CMV status at different time intervals." (PMID 36232655, 2022).
breast cancer (36 papers, 2007 to 2025). A primary or metastatic malignant neoplasm involving the breast. "Other research has shown that Ccl3 and Ccr1 expressed by tumor-associated Macrophages is associated with enhanced interaction with breast carcinoma cells and metastatic seeding to the lung." (PMID 39026350, 2024). "IL4 signaling in macrophages also transcriptionally regulated other genes causally associated with mammary cancer lung metastasis, including Ccl2, Csf1, Ccr1, Hgf and Flt1." (PMID 36077870, 2022). "The aim of this study was to clarify the regulatory mechanism underlying transcriptional activation of the CCR1 gene in response to epidermal growth factor (EGF) stimulation in breast cancer cells." (PMID 29212252, 2017). "In this study, we aimed to investigate the expression status of CCR1 in breast cancer tissues, the functional relevance of CCR1 in breast cancer metastasis, and the mechanisms underlying the regulation of CCR1 expression in breast cancer cells." (PMID 29212252, 2017). "Furthermore, IL4 signaling in macrophages regulated the transcript abundance of several other genes already causally associated with mammary cancer lung metastasis including Ccl2, Csf1, Ccr1, Hgf and Flt1." (PMID 36077870, 2022). "This strongly suggests that CCR1 plays a functional role in the migration behavior of basal breast cancer cells in an environment enabling close cell–cell contacts between ASCs and tumor cells, as found in invasive carcinomas in the mammary fat pad." (PMID 37444610, 2023). "CCL16 also activates the angiogenic process in vascular endothelial cells via CCR1 and shows an elevated expression in lymphoid neo-organogenesis of breast cancer." (PMID 33500726, 2021). "We therefore immunolocalized CCL5, as well as CCR1, 3 and 5, in 111 human breast carcinoma tissues and correlated them with clinicopathological characteristics." (PMID 33671956, 2021). "When we correlated immunoreactivity for CCL5, CCR1, 3 and 5 with the clinicopathological factors of 111 breast carcinoma tissues." (PMID 33671956, 2021). "Activation of EGFR signaling via CCR1 has been shown to contribute to breast cancer invasion and metastasis." (PMID 32963283, 2020). "The CCR1 mediated interaction between macrophages and breast cancer cells induced a chemokine cascade that enhanced metastasis." (PMID 32963283, 2020). "CCL7 is a ligand for CCR1–3 receptors, among which expression of CCR3 has recently been shown to be associated with luminal-type breast cancers." (PMID 31419632, 2019). "Shin, S.Y.; Lee, D.H.; Lee, J.; Choi, C.; Kim, J.Y.; Nam, J.S.; Lim, Y.; Lee, Y.H. C-C motif chemokine receptor 1 (CCR1) is a target of the EGF-AKT-mTOR-STAT3 signaling axis in breast cancer cells." (PMID 31146450, 2019). "CCR1 can be expressed on the surface of breast cancer cells, accelerating tumor angiogenesis in the tumor microenvironment." (PMID 29915688, 2018). "Further study showed that CCL7 mainly promotes breast cancer cell proliferation via binding to its receptor CCR1." (PMID 29915688, 2018). "In conclusion, the AKT-mTOR-STAT3 signaling axis contributes to EGF-induced CCR1 expression, which promotes invasion and metastasis in breast cancer cells." (PMID 29212252, 2017). "In summary, we propose a signaling mechanism by which EGF up-regulates the expression of CCR1 through the AKT-mTOR-STAT3 axis in MDA-MB-231 breast cancer cells." (PMID 29212252, 2017). "We observed that CCR1 mRNA was abundantly expressed in various breast cancer cell lines, including MDA-MB-231, MDA-MB-361, MCF7, and T47D cells, as compared with the levels in normal MCF12A breast epithelial cells." (PMID 29212252, 2017). "To investigate the role of CCR1 in human breast cancer, we first evaluated its expression in a tissue microarray composed of human breast invasive ductal carcinoma (IDC) and their adjacent peripheral normal tissues." (PMID 29212252, 2017).